CXCR5 (C-X-C motif chemokine receptor 5)
Diseases named in the same sentence as CXCR5 in open-access papers (continued):
Sharing a sentence is not in itself a finding about the gene and the disease.
tumor (continued). "Thereby, we focused on whether CXCR5 could initiate a miRNA mediated network to drive the differentiation of tumor cells into Schwann-like cells in PNI of SACC, promising to identify new biomarkers and offer cancer therapeutic targets." (PMID 34114971, 2021). "Therefore, when considering the specific effect of CXCL13 in the tumor microenvironment, attention needs to be paid to the expression status of CXCR5 on cancer cells." (PMID 35693216, 2021). "Both in vitro and in vivo experiments confirmed the original hypothesis that the overexpression of CXCR5 improves the migration of CAR-T cells to the CXCL13-positive tumor site, as shown directly by tracking CAR-T cells in vivo." (PMID 34553036, 2021). "Positive CXCR4 expression was found in 195 (79.9%) samples of tumor tissues and 12 (4.9%) samples of normal tissues, while positive cases for CXCR5 and CCR7 were 155 (63.5%) and 117 (48.0%) samples of tumor tissues and 15 (6.1%) and six (2.5%) samples of normal tissues, respectively." (PMID 32896997, 2020). "However, researchers must be cautious as both must be considered with respect to tumor type and CXCR5 tumor expression." (PMID 33193299, 2020). "CXCR5 expressing B cells stimulated by CXC13 coupled CpG-ODN can trigger the cytolytic effect of CD8 + T cells leading to the abrogation of metastasis in 4T1.2 tumour-bearing mice." (PMID 31901949, 2020). "To test whether tumor repression in KO mice was contributed by compromised Tfr response, we first examined Tfr population within tumor using CXCR5-GFP reporter mice." (PMID 32477338, 2020). "CXCR5 can regulate B-cells, T cells, and dendritic cells in secondary lymphoid tissue, which could also contribute to tumor escape from the surveillance of immune system." (PMID 33324682, 2020). "Tumor-infiltrating CD8+CXCR5+ T cells also highly express PD-1 and ICOS, which may indicate that blocking CD8+ T cell immune checkpoint inhibitors could serve as a therapeutic option in the future." (PMID 31663864, 2019). "Moreover, the levels of PD-1 and ICOS markers expressed by CD8+CXCR5+ T cells were significantly higher in tumor tissue than in the matched blood or peritumoral liver tissues or in healthy blood samples." (PMID 31663864, 2019). "Importantly, the percentage of tumor-infiltrating CD8+CXCR5+ T cells correlated negatively with microvascular invasion and early recurrence." (PMID 31663864, 2019). "Importantly, although IL-21 is mainly secreted by T follicular helper cells, we found that tumor-infiltrating CD8+CXCR5+ T cells are able to induce B cells to differentiate into IgG-producing plasmablasts." (PMID 31663864, 2019). "Moreover, Th1 and Th17 subtypes contribute to the upregulation of peripheral CD4+CXCR5+ T-cells in patients with metastasis or high tumor grade." (PMID 31354634, 2019). "Furthermore, CXCL13 was required for the clustering of CXCR5+ ILC3s with mesenchymal stromal cells in the tumor microenvironment, which supported lymph node metastasis." (PMID 31507605, 2019). "With regard to our data, more peripheral CXCR5+CD4+ Tfh cells might be recruited to liver tissues in response to the tumor, ultimately leading to a decrease in circulating CXCR5+CD4+ Tfh cells in HCC patients." (PMID 25689070, 2015). "Among various chemokines, C-X-C motif ligand 13 (CXCL13, also named as B-cell attracting chemokine 1 (BCA-1)) is thought to play an important pro-tumor role in colon, prostate, and breast cancers through the interaction with its receptor, the C-X-C chemokine receptor 5 (CXCR5)." (PMID 25966773, 2015). "We further investigated CXCR5 expression in relation to tumor stage (T) and nodal metastasis (N)." (PMID 25271023, 2014). "Immunohistochemistry studies also confirmed the expression of human CXCR5 by tumor cells." (PMID 23936541, 2013).
tumor (continued). "Furthermore, evidence suggests that CXCL13, together with CXCR5, may play a crucial role in regulating tumor occurrence and metastasis via the PI3K/AKT pathway, as demonstrated in studies on CRCs." (PMID 40943634, 2025). "In addition, the higher proportions of CXCR5+ non-Treg cell populations among CD4+ T-cells from patients with CLL were significantly associated with a lower tumor distribution (TD) value, predominantly representing lymph node involvement." (PMID 40427031, 2025). "The presence of high levels of immunosuppressive T regulatory cells and low levels of CXCR5+ cells in TDLNs of patients who relapse further reinforces this hypothesis, reflecting the weakness of the immune system and tumour-induced immunosuppressive environment in TDLNs." (PMID 39474426, 2024). "Particularly, the signaling of CXCL13 through its receptor, CXCR5, has recently been associated with promalignant intracellular pathways such as PI3K/AKT, MEK/ERK and Rac-GEF/Rac, leading to cell survival, proliferation and migration in different tumor entities." (PMID 36077611, 2022). "However, tumor growth was accelerated in CXCR5 or Rag1-KO mice." (PMID 35552285, 2022). "CXCR5+CD8 T cell persistence following ICB may generate a greater antibody repertoire based on their known B cell interactions that could be beneficial for tumor eradication or generate organ specific detriments and IMAEs." (PMID 36314014, 2022). "However, CXCR5+CD8+T cells largely represent tumor-specific CD8+T cells." (PMID 34035252, 2021). "Therefore, tumor cell surface CXCR5 was evaluated by flow cytometry in this study." (PMID 35693216, 2021). "The selective expression of CCR5 and CXCL13 in neoantigen-specific T cells further suggests that a key feature of CPI-responsiveness is the ability to sustain ongoing priming and recruitment of tumour reactive T cells supported by CXCR5+ lymphocytes, which may include T and B cells." (PMID 33508232, 2021). "Furthermore, the overexpression of CXCR5 on intratumoral natural killer (NK) cells has been speculated to be involved in their migration in the tumor site, where NK cells participate in tumor immunosurveillance." (PMID 34947813, 2021). "To investigate whether dLNs derived Tfr cells were involved in tumor control, we set up BM chimera mice by mixing bone marrow cells derived from Foxp3DTR mice (50%) and Cxcr5–/– mice (50%) and injecting the mixtures into sub-lethally irradiated CD4–/– recipients." (PMID 32477338, 2020). "These CXCL13-expressing FDCs were found to colocalize with CXCR5+ follicular helper T cell-like cells, suggesting that CXCL13 expression in tumor TLSs could contribute toward generation of humoral immune responses via recruitment of CXCR5+ immune cells into the GC." (PMID 29312327, 2017). "Thus, the CXCL13/CXCR5 axis might be pivotal factors for the Tfh/B cell infiltration into tumor sites and subsequent tumor formation." (PMID 24966464, 2014). "In vivo, tumor-derived CXCL13 suppressed tumor growth, increased intratumoral CD8+ T cell infiltration, and enriched CXCR5+TCF1+CD8+ stem-like T cells." (PMID 42146336, 2026). "Both the co-expression and single expression of CXCR5 or CCR6 in HER2-CAR T cells resulted in a markedly higher positive staining for CD4 + and CD8 + CAR T cells in the tumor tissue compared to those in the HER2-CAR T cell and Control-T treatment groups." (PMID 40764989, 2025). "Recent evidence highlights the elevated expression of CXCR5+ CD8+ T cells and their cytotoxic role against autologous tumor cells in DLBCL." (PMID 40091778, 2025). "The high specificity of CXCR5 and CCR6 for their cognate ligands minimizes off-target risks while exploiting their functional roles in recruiting and activating tumor-specific T cells within the TME." (PMID 40764989, 2025). "As expected, CXCR5 + CD4 + Tfh cells were localized in TLSs and also present in the tumor center and invasive margin, with increased numbers in early CRC." (PMID 40287532, 2025).
tumor (continued). "In parallel, CD4+/CD8+ CXCR5+T follicular helper cells and CD8+CD103+ tissue-resident memory T cells were observed infiltrating in tumor tissues, Moreover, CD200 expressing B (CD20+CD200+) and T cells (CXCR5+CD200+) accumulated in the DCB groups." (PMID 40404633, 2025). "The treatment of mice with anti–PD-L1 combined with bacteria provided analogous control of tumor growth as the combination of the antibody with apyrase as well as a similar increase in TNF-α+Granzyme B+ and CXCR5+ CD8 TILs." (PMID 41042869, 2025). "Additionally, co-occurrence of tumor-associated CD8+ T cells and CD20+ B cells improves survival in metastatic melanoma patient samples, where TLS in CD8+CD20+ tumors stained for CXCL13, CXCR5, and CD20, and B cell-enriched tumors had increased TCF-7 naive and/or memory T cell levels." (PMID 40475770, 2025). "Further research should examine CXCR5 and LAG‐3 expression in lymphoid tissues to better understand their role in the tumor microenvironment." (PMID 40091778, 2025). "The mice treated with HER2-CAR T cells, either co-expressing or singly expressing CXCR5 and CCR6, exhibited significantly improved long-term tumor control compared to those in the Control-T and HER2-CAR T groups." (PMID 40764989, 2025). "Collectively, our findings suggest that the co-expression of CXCR5 and CCR6 confers a distinct advantage, providing synergistic anti-tumor effects over the single expression of either receptor in HER2-CAR T cells." (PMID 40764989, 2025). "Our study revealed significant enrichment of CXCR5+CD4+ and CXCR5+CD8+ T cell in ES-SCLC patients exhibiting robust immunotherapy responses, suggesting their cooperative roles in shaping anti-tumor immunity." (PMID 40404633, 2025). "CXCR5 + BCL6+ Tfh cells were rare in the “Tumor-Adj” and “Tumor-Dis” sites of the tumor-bearing testis and in the contralateral testis." (PMID 38649788, 2024). "A human CXCR5-targeting CAR T cell showed in vitro efficacy against a range of cell lines and patient-derived primary tumor cells, and tumor eradication in an NSG model of B-NHL." (PMID 39335157, 2024). "Furthermore, our study identifies TLS-associated cell types (B lineage cells, CD4_C8_CXCR5 and CD8_C8_CXCL13 T cells, and CXCL13+ CAFs) and TCA signatures (EBVhigh-TCA-wP) as biomarkers for the prognosis and immunotherapy response of NPC, corroborating TLS’s contribution to tumour development." (PMID 39231979, 2024). "This construct co-expressed CXCR5 and IL-7 (C5/IL7) within the conventional NKG2D-CAR backbone, addressing both challenges, i.e., effective tumor penetration and sustained presence." (PMID 39450160, 2024). "Patients with high CCR5, CCR7, CXCR4, and CXCR5 expression on tumors and high CXCR4 expression on tumor-infiltrating lymphocytes were less likely to have a chemotherapy response compared to others." (PMID 39001456, 2024). "Cytokine-based signalling pathways, such as the CXCL13/CXCR5 axis and the CCL19,21/CCR7 axis, mediate the recruitment of B cells and TLSs in tumours." (PMID 36890557, 2023). "Overall, our analyses illustrate ICI-mediated release of T cell checkpoint engagement of tumor-specific, PD1+ TOX+ CD8 T cells upregulates CXCL13, which subsequently recruits CXCR5+ B cells and Tfh to form TLS in the TME." (PMID 37435085, 2023). "Our cell-cell interaction analysis highlighted CXCR5+ B cells as the dominant antigen presenting cells in ICI OT-R TME, presenting antigens to both tumor-reactive CD8 T cells and CD4 Tfh cells and through MHC I and MHC II pathways, respectively." (PMID 37435085, 2023). "In ICI OT-R tumors, the increase of TLS-associated CXCR5+ B and Tfh cells were correlated with increased mRNA expression of CXCR5’s ligand, CXCL13, by activated, tumor reactive CXCL13+ CD8 T cells." (PMID 37435085, 2023). "CXCR5 binds to CXCL13 and regulates the growth, proliferation, invasion, and metastatic ability of tumor cells." (PMID 37626511, 2023).
tumor (continued). "CXCR5 is the receptor for CXCL13, which is secreted at the tumor site to recruit B cells from circulation." (PMID 36012390, 2022). "Because the CXCL13/CXCR5 axis can orchestrate the immunological dynamics in the TME, it would be interesting to investigate the involvement of miR-934–mediated tumor-macrophage crosstalk in the systemic metastasis of other cancer types." (PMID 36248881, 2022). "In addition, our study revealed that MXRA8 expression correlated with the expression of multiple metastasis-associated chemokines (CXCL12, CXCL13, CCL9, CCL21, CXCR4, CXCR5, and CCR7), suggesting that MXRA8 may be involved in tumor invasion and metastasis by regulating the secretion of chemokines." (PMID 36703779, 2022). "This demonstrates the importance of CXCR5+CD8 T cells within the tumor microenvironment and surrounding tissues to patient outcomes and identifies possible tumor eradication mechanisms utilized by CD8 T cells." (PMID 36314014, 2022). "T cells secrete CXCL13 to recruit CXCR5+ immune cells to the TME, thus initiating jointly anti-tumor immune responses." (PMID 35392977, 2022). "CXCR5+CD8 T cells upregulate CD107a, proliferate, and induce specific cell lysis of in vitro co-cultured tumor cells." (PMID 36314014, 2022). "In metastatic CRC, tumor-expressed miR-934 led to increased production of CXCL13 in M2-like TAMs and activated a CXCL13/CXCR5/NFkB/p65/miR-934 positive feedback loop in cancer cells." (PMID 36248881, 2022). "Within cancer CXCR5+CD8 T cells have risen as potential prognostic markers for overall survival and are functionally cytotoxic within tumor microenvironments." (PMID 36314014, 2022). "The adhesion of MCL tumor cells to stromal cells is attributed in part to the high level of expression of functional CXCR4, CXCR5 chemokine receptors, and VLA-4 adhesion molecules on the surface of MCL." (PMID 35804999, 2022). "Tumors express CXCR5 and produce its ligand, CXCL13, to recruit B cells and T cells into tumor microenvironments where tertiary lymphoid structures, resembling germinal centers, are developed and antibody production occurs." (PMID 36314014, 2022). "To further explore why tumor relapse occurs in the NSG mouse model, we analyzed the persistence of CXCR5 CAR-T cells in vivo at the time of JeKo-1 outgrowth." (PMID 33431832, 2021). "Among them, CXCR5 and CXCR6 have been found to play a role of tumor suppressor genes in the prognosis, which is controversial." (PMID 33829065, 2021). "It is reported that the expression levels of CX3CR1, CXCR4, CXCR5, and CCR7 in tumor tissues are significantly increased, which is able to affect the survival time of patients." (PMID 34603645, 2021). "Due to the importance of CXCR5+PD‐1+ CD8 T cells for response to ICB in mice, several other studies have looked in tumor samples for a human analogue of this progenitor T cell." (PMID 33098668, 2021). "Regarding transcription factors, the two tumor-specific CD8+T subsets expressed comparable Eomes and TOX, while PD-1+CXCR5+CD8+T cells show higher T-bet and TCF7 expression." (PMID 34035252, 2021). "The CXCL13/CXCR5 axis drives CD40+ MDSC migration to gastric cancer, leading to immune escape and tumor progression." (PMID 34947813, 2021). "And further analysis validates that CXCR5+CD8+T cells are mainly present in tumor and peritumor tissues, and only 3% of CD8+T cells presented in peripheral blood express CXCR5." (PMID 34035252, 2021). "FL tumor cells expressing CXCR4, CXCR5 and CCR7 home in both BM and LN, and the interaction of CXCR12 expressed on BM stromal cells of the lymph node/BM with CXCR4 expressed by tumor cells, has been found to play a critical role in this context." (PMID 34395425, 2021). "In an in vitro stress assay, recursive antigen encounter of the CXCR5 CAR-T cells resulted in extended maintenance of proliferative capabilities and anti-tumor effector function." (PMID 33431832, 2021).
tumor (continued). "Then, we used flow cytometry to label and analyze the number of CCR3+, CCR9+, CCR10+, CXCR2+, CXCR5+, and CXCR6+ cells expressed different isotype antibodies including IgA, IgG, and IgM in the lung metastases of cKO and control tumor-bearing mice." (PMID 33707428, 2021). "Furthermore, tumor relapse might occur due to CXCR5 CAR-T cell exhaustion." (PMID 33431832, 2021). "In conclusion, the present study demonstrated that the expression levels of CXCR4, CXCR5 and CCR7 were significantly higher in tumor tissues." (PMID 32896997, 2020). "CXCR3 and CXCR5 (e.g., CXCL10-CXCR3, CXCL11-CXCR3, and CXCL13-CXCR5), which belong to the CXC chemokine receptor family, were found highly expressed in tumor T cells." (PMID 32549766, 2020). "Another subset of auxiliary T cells, the T follicular helper (Tfh) CD4+ lymphocytes, defined by CXCR5 chemokine receptor expression and the Bcl6 transcription factor, are found within and around CRC tumor nests and tumor draining lymph nodes (tdLN)." (PMID 33381121, 2020). "Several of these markers including MS4A1, CXCR5, and CXCL13 are also suppressed across all stages (Stages 1–4) with respect to normal, further emphasizing their role in sustaining tumor behavior within LSCC." (PMID 32293332, 2020). "Expression levels of CXCR4, CXCR5 and CCR7 were significantly higher in tumor tissues, and expression of CXCR5 and CCR7 were independent prognostic factors for survival." (PMID 32896997, 2020). "Circulating, tumor infiltrating, and lymphoid CXCR5+ CD8 T cells also express PD-1 and Tim-3 but are functionally less exhausted than CXCR5- CD8 T cells." (PMID 31275308, 2019). "FACS results confirmed the activated state of FcγRIIlow/− B cells as following: most FcγRIIlow/− B cells from HCC tumours displayed a CD69+BTLA− activated phenotype with reduced B-cell follicle homing molecules CD62L, CXCR5 and CCR6." (PMID 27853178, 2016). "In both the bone marrow and tumor tissues of WT mice, a similarly high percentage of MDSC were positive for CXCR5 expression (77.33 ± 3.29% in bone marrow and 72.93 ± 2.05% in tumor tissue; p > 0.05)." (PMID 26462153, 2015). "In the tumor samples from NOD/SCID mice injected with A549-Luc-CXCL13 cells and BaP-treated Cxcr5+/+ mice, the expression of E-Cadherin was low, while the N-Cadherin and nuclear β-catenin were high." (PMID 26565418, 2015). "Other than CXCR4, we and other groups have also shown the involvement of CXCR5 and CCR9 in survival and metastasis of tumor cells in different malignancies." (PMID 25296976, 2014). "The fact that pre-incubation of 2F7 cells with neutralizing antibody to CXCR5 substantially delays the time to death in the model provides additional evidence that the CXCR5/CXCL13 axis could potentially be playing an important role in tumor development in the model." (PMID 23936541, 2013). "We have previously reported that 2F7 cells show chemotaxis towards human CXCL13 in vitro; others have reported or inferred that murine CXCL13 can act on human CXCR5, and that human CXCL13 can induce proliferation of tumor cells in some cancers." (PMID 23936541, 2013). "We used immunohistochemistry to identify cells expressing CXCR1, CXCR2, CXCR3, CXCR4, CXCR5 and CCR1 in the tumour islets and stroma in 20 patients with surgically resected NSCLC." (PMID 20429924, 2010). "Moreover, the combination of chemokine receptor (including CCR2b and CXCR5) and IL-7 armoring has been demonstrated to boost CAR T-cell expansion and anti-tumor activity in immunodeficient mouse tumor models." (PMID 41019052, 2025). "CXCR5+ PD-1+ Tfh-like cells that made up a minor fraction of total CD4+ T cells were a significant component of the CLTCH129>Q-specific response, and these also subsequently deceased during progressive tumor growth." (PMID 40196575, 2025).